CCL2 (C-C motif chemokine ligand 2)
Diseases named in the same sentence as CCL2 in open-access papers (continued):
Sharing a sentence is not in itself a finding about the gene and the disease.
infection (continued). "And the mRNA levels of IL-6, IL-8, and CCL-2 in brain tissue were also increased by CA16 infection, and SAM decreased them to some extent." (PMID 30186868, 2018). "Neurons and astrocytes constitutively express low levels of CCL2 in the healthy brain, as seen in our results, but some studies have noted a microglial requirement for upregulation after infection." (PMID 30442185, 2018). "CCL2 or monocyte chemoattractant protein 1 (MCP‐1) recruits monocytes to the site of infection, ischaemia or inflammation." (PMID 27973687, 2017). "Only GJ18 experienced any systemic pro-inflammatory response with transiently increased plasma concentrations of IL-12, CXCL8, and MIF by day 1 to 2 post-infection that rapidly resolved to baseline and later increases in CCL2 and CCL11." (PMID 29259582, 2017). "Several chemokines Ccl2, Ccl5 and Ccl6, and genes from the lymphocyte antigen 6 superfamily, Ly6a, Ly6e and Ly6f were found to be modulated only with V3000 infection in brain." (PMID 28446152, 2017). "Inflammatory factors, such as TNFα and chemokines including Ccl2, Ccl5, Ccl9 and Cxcl2, were upregulated in response to more than one type of infection, particularly L. m and VSV." (PMID 28088779, 2017). "This indicates that the secreted CCL2 is most probably involved in the recruitment of CD172a+ cells during an infection with EHV-1 neurological strains." (PMID 28241864, 2017). "Inflammatory monocytes are recruited to tissues in response to infection or tissue damage via chemokine (C-C motif) ligand 2 (CCL-2)." (PMID 28233125, 2017). "The receptors that bind the main chemokine attractants of monocytes (CCR1 for CCL3 and CCR2 for CCL2) that mediate monocyte recruitment to sites of infection were equally expressed on the monocytes of the three groups." (PMID 29116124, 2017). "MCP-1/CCL2 is a potent chemotactic factor for monocytes/macrophages and dendritic cells to the sites of inflammation caused by infection or tissue injury." (PMID 28165033, 2017). "CCL2 showed the least changes in expression compared to other cytokines following FIPV 79–1146 infection." (PMID 28388950, 2017). "MCP-1 (CCL2) as well as RANTES (CCL5) were elevated in cardiac tissue 7 days after infection and significantly declined in the chronic phase." (PMID 28352641, 2017). "For monocytes, this suggests that about 70% of the infiltration in response to TMEV infection is dependent upon the CCL2:CCR2 axis and about 30% requires the CCL7:CCR2 axis." (PMID 29202854, 2017). "By comparison, CCL2 and IL-6 were significantly reduced during Opal524R infection at day 2 postinfection." (PMID 29138302, 2017). "CCL2 was induced in the nasal passages (NPs) upon infection, and co-transfer of in vitro-expanded WT and Ccr2−/− γδT17 cells into infected mice revealed an intrinsic requirement of CCR2 for γδT17 cell accumulation in NP." (PMID 28580944, 2017). "It has been reported that human cytomegalovirus (HCMV) tegument protein pp71 and the viral G protein coupled receptor (vGPCR) of human herpesvirus 8 (HHV-8) lead to an increased expression of CCL2 during infection." (PMID 28241864, 2017). "Even so, carvedilol therapy during acute phase of infection was able to modulate the CCL2 and intensify the production of the regulatory cytokine IL-10 in serum from infected mice." (PMID 28377930, 2017). "Trafficking of monocytes to the site of inflammation or infection requires coordinated action by various chemoattractant molecules, including CCL2, which are released by inflamed tissue." (PMID 29056937, 2017). "Classical monocytes, which express CCR2 and migrate to inflammatory sites in response to CCL2, are resistant to HIV-1 infection, whereas CD16+ monocytes are highly susceptible to infection." (PMID 28661459, 2017). "In contrast, only a few immunity-related mRNAs encoding chemokines (Cxcl10, Cxcl1, Ccl2) and the invariant chain (CD74) were up-regulated in multiple host cell types after infection." (PMID 28775382, 2017).
infection (continued). "In particular, either infection itself or exposure to viral proteins can induce an increase of CCL2 production in monocyte-derived macrophages (MDMs)." (PMID 28661459, 2017). "Quantitative reverse transcription PCR (RT-qPCR) was used to investigate the effect of Bindarit on CCL2 gene expression during infection with A/Ca (H1N1), a representative, currently circulating IAV subtype, in a human epithelial cell (A549) line." (PMID 28435679, 2017). "CCL2 is a potent chemokine involved in the recruitment of monocytes to sites of tissue injury and infection." (PMID 28143606, 2017). "It is very well possible that the full-length gp2 protein is involved in the induction of CCL2 in the early stage of infection." (PMID 28241864, 2017). "There was a significant decrease in the concentrations of TNF-α, IL-6, IL-8, and CCL2 present in the vaginal washes following the Us2 mutant infection compared with HSV-2 infected mice." (PMID 28827540, 2017). "In this context, it is notable that CCL2 immunoreactivity is strongly upregulated in CA1 neuron apical dendrite tufts located in the stratum lacunosum moleculare at 6 h after infection." (PMID 29202854, 2017). "It has been reported that infection of alveolar epithelial cells with influenza A virus can strongly induce the release of monocyte chemoattractants CCL2 and CCL5 followed by a strong recruitment of monocyte transepithelial migration." (PMID 28241864, 2017). "Wild-type infection also induced IL-6, CCL2 (MCP-1), and CXCL1 at day 2 postinfection and suppressed IL-15 production compared to levels in mock-infected animals." (PMID 29138302, 2017). "Analysis of mRNA expression in pooled DRG revealed that expression of mRNA encoding CXCL13 was significantly elevated at 2 and 4 weeks following B. burgdorferi administration, while levels of CCL2 mRNA were higher at 4 weeks following infection." (PMID 28202084, 2017). "Critically, on day 4 post-infection, IL-1β, TNFα, IL-6, CCL2 and CCL5 concentrations were significantly reduced in BAL fluid while IL-6 and IL-18 were reduced in the sera." (PMID 27283237, 2016). "Cortex showed the highest release of CCL2 and IL-6 from both 48 and 72 hpi (hours post infection) compared to other regions." (PMID 26931456, 2016). "This protection does not result from an improved viral clearance or increased immune resistance to the virus, but correlates with a dampened pulmonary CTL response and a strongly suppressed expression of the chemokine CCL2 during later stages of infection." (PMID 26815999, 2016). "In the acute infection model, CCL2 and CXCL8 protein releases were detected in supernatants of the cells of all donors only after 9 h and were within the levels of the non-infected control HPBCs." (PMID 27446812, 2016). "Pro-inflammatory cytokines (IFN-γ, IL-18, IL-6, TNF-α) and chemokines (CCL2, CCL5, CCL7, CXCL1, CXCL10) were found to be increased in sera of ZIKV-infected mice, indicating that infection causes systemic inflammation." (PMID 27163257, 2016). "This increased protection correlates with a dampened pulmonary cytotoxic T cell response and a strongly suppressed expression of the chemokine CCL2 during later stages of infection." (PMID 26815999, 2016). "Expression of the chemokine CCL2 (also named MCP-1) is particularly suppressed in the lungs of A20AEC-KO mice during later stages of infection." (PMID 26815999, 2016). "In the persistent model of infection, the release of CCL2 by the HPBCs of all donors increased with time from 9 to 48 h and was within the levels of the non-infected HPBCs." (PMID 27446812, 2016). "The chemokines Ccl2, Ccl7 and Cxcl1 were also expressed at higher levels in cPLA2α−/− compared to cPLA2α+/+mice 12 h after infection, but at 24 h they decreased to a greater extent in cPLA2α−/− than cPLA2α+/+mice." (PMID 27501951, 2016).
infection (continued). "In our previous analyses, we found that CCL2 Tg mice exhibited an improved pneumococcal clearance after infection with S. pneumoniae, but at the same time developed OP lesions." (PMID 27282780, 2016). "At 29 days post-infection, Ifng, Gzmb, and Il6 mRNA levels strongly decreased whereas a strong up-regulation of Ptgs2 and in a lesser extent Nos2 and Ccl2 mRNA levels remained." (PMID 28018318, 2016). "Together, these results show that the protection of A20AEC-KO mice from infection results from a reduced CCL2-dependent recruitment of innate immune cells to the lungs of infected mice." (PMID 26815999, 2016). "For example, CCL2 is a member of the C-C chemokine family, which regulates the recruitment of myeloid cells into inflamed sites during pathogen infection." (PMID 27786298, 2016). "Within the genes coding for the chemokines, the gene coding for CCL2 showed a distinct down-regulation 6 h post-infection." (PMID 27310007, 2016). "By 14 h after infection, lower serum levels of CCL2 were detected in mice infected with biofilm-released cells, when compared with their planktonic infected counterparts." (PMID 27729907, 2016). "ELISA measurements confirmed a robust induction of CXCL1, G-CSF, and CCL2 in the peritoneal cavity of mice infected with E. coli 127 in comparison with infection with any of the other bacteria." (PMID 27713743, 2016). "The only gene specific to astrocytes with greater than four-fold upregulation was Ccl2, a chemokine known to be highly expressed by astrocytes following infection or injury in the CNS." (PMID 26214311, 2015). "CCL2 neutralization potently reduced the number of p24 Gag+ cells during the course of either productive or single cycle infection with HIV-1." (PMID 25608886, 2015). "Of note, although the known neutrophil chemoattractants CXCL1 (KC) and CCL2 (MCP-1) increased following infection, the levels were similar in aged vs. young mice." (PMID 25595646, 2015). "We next examined the concentration-dependency of the effect of anti-CCL2 Ab on HIV-1 DNA levels after 7 days of infection." (PMID 25608886, 2015). "CCL2 attracts monocytes, memory T cells, and dendritic cells to sites of tissue injury, infection, and inflammation." (PMID 26085826, 2015). "In fact, we report here that neutralization of CCL2 potently reduces the proportion of p24 Gag+ cells during the course of either a productive infection with R5 HIV-1BaL or a single cycle infection with (VSV-G) HIV-1." (PMID 25608886, 2015). "At post-infection day 7, the levels of pulmonary chemokine cytokine, especially CCL2, was significantly increased by PR8-infection and which was significantly decreased in groups treated with oseltamivir plus fraction." (PMID 26098681, 2015). "The expression level of CCL2 increased significantly at the early infection phase and reached the peak at 14 dpi and still showed high expression at the late infection phase." (PMID 26070790, 2015). "In particular, at 14 days post-infection the median CCL2 secretion in uninfected cells was 8,410.9 ± 1,027.5 (SE) pg/ml, whereas it increased to 18,982.9 ± 2,102.1 (SE) pg/ml (p < 0.001) upon infection with HIV-1." (PMID 25608886, 2015). "The up-regulation of CCL2 indicated that the worm of A. cantonensis had migrated into the mouse brain at an early infection phase." (PMID 26070790, 2015). "A decrease of HIV-1 DNA accumulation was observed in MDM exposed to anti-CCL2 Ab both 20 h before or at the time of infection [0.10 ± 0.02 (SE) and 0.16 ± 0.07 (SE) fold vs. control Ab, respectively (p < 0.001); n = 3]." (PMID 25608886, 2015). "CCL2/MCP-1 reported to induce chemotaxis of human microglia, indicating that uninfected cells can be induced to migrate areas of active infection or BBB disruption where CCL2/MCP-1 is released in response to Tat." (PMID 26113810, 2015). "In contrast, in anti-CCL2 Ab treated MDM the levels of HIV-1 DNA at 7 days post-infection were similar to those found 4 days after infection [0.96 ± 0.45 (SE) fold]." (PMID 25608886, 2015).
infection (continued). "To further investigate the mechanisms underlying the inhibition of HIV-1 replication associated with CCL2 neutralization in MDM, we quantified the levels of viral DNA that accumulated at different time points post-infection." (PMID 25608886, 2015). "In general, the production of cytokines and chemokines increased from baseline levels during the infection and peaked on day 3 pi although levels of the chemokine CCL2 (MCP-1) peaked on day 1 pi and decreased thereafter." (PMID 25938762, 2015). "This chemokine can also bind CCR2, the receptor for CCL2, and both it and CCL2 have additive functions in monocyte homeostasis and recruitment during infection." (PMID 26107875, 2015). "This is consistent with a role for CCL2 in increased macrophage numbers at sites of infections with other helminths, and with microbial pathogens." (PMID 25144366, 2014). "On the other hand, Nod2−/− mice displayed reduced production of the chemokine CCL2, which ultimately lead to impaired adaptive immunity and impaired clearance of C. rodentium after d14 of infection." (PMID 25254654, 2014). "In the early phase of the infection, cellular antiviral immunity is initiated by Kupffer cells releasing CCL2, resulting in the recruitment of CCL3-producing monocytes and pDCs, which attract NK cells." (PMID 24646914, 2014). "Gavage infection resulted in high levels of IFNγ, CCL2 and IL-6 already at day 2, followed by the gradual decrease of these cytokines." (PMID 25919005, 2014). "Our results points to CCL2/CCR2 signaling as a crucial element in the development of neuroinflammation in the first days following a peripheral infection." (PMID 25065370, 2014). "We also show that the expression levels of several chemokines regulated by NF-κB signaling (Ccl2, Ccl3 and Ccl5) were similarly elevated at early infection." (PMID 25116007, 2014). "MCP1/CCL2 gene transcript in the family of cytokines and chemokines was significantly increased following Cpn infection." (PMID 25540075, 2014). "Although RRV-induced IL-6, TNF-α and CCL2 were lower in the OA hOBs compared to infected controls during early infection, the expression of these osteotropic factors in OA hOBs, with the exception of TNF-α, was significantly elevated at 96 hpi." (PMID 25407789, 2014). "The pathology of schistosome infection in the liver appears tightly connected to the action of chemokines (like Ccl2), which control the migration of immune cells to the site of infection, and mediate the chemotaxis of HSCs and macrophages." (PMID 25116007, 2014). "CD11b+Ly6chighLy6G− inflammatory monocytes are reported to contribute to T. brucei-induced pathogenicity development through their production of TNF, whereby in the acute phase of infection their emigration from the bone marrow is CCL2/CCR2-dependent." (PMID 25255103, 2014). "We propose the role of CCL2 in PRRSv infection primarily involves monocyte recruitment in lung, and is unrelated to mechanisms of fetal death or survival." (PMID 25479904, 2014). "TNF-α, IFN-γ, IL-6 are cytokines important for mounting a proper adaptive antiviral response to HSV-2, while CCL2 can attract monocytes and T cells to the site of infection." (PMID 25117537, 2014). "The infection of MP with MOPV induced robust expression of the CCL2, 3, 4, 5, 7, and 13 genes, and of the CXCL9, 10, and 11 genes, in particular." (PMID 24421914, 2014). "In this study, we found that changes in the expression levels of several chemokines (Ccl2, Ccl3 and Ccl5) mirrored those of NF-κB signaling (similarly peaking 32 days post-infection)." (PMID 25116007, 2014). "Our data clearly show a role for CCL2 in the recruitment of monocytes into liver tissue during infection with schistosomes." (PMID 25144366, 2014). "In marked contrast, rJ2.2 infection of mice that transgenically express CCL2 in the brain (CCL2 Tg) ineffectively cleared virus and rapidly succumbed to the infection." (PMID 25250029, 2014).
infection (continued). "Two important chemokines are interleukin 8 (IL8 or CXCL8), a potent recruiter of neutrophils to sites of infection, and chemokine ligand 2 (CCL2), which induces the migration of monocytes from blood to become tissue macrophages." (PMID 25479904, 2014). "HIV-1 envelope glycoprotein gp120 induces, independently of infection, the release of CCL2 from macrophages." (PMID 23555755, 2013). "Compared to the other inbred mouse strains investigated, C3HeB/FeJ mice displayed elevated serum levels of IL-6, TNF-α and extremely high levels of the chemokine CCL2 at 3 and 5 days post infection." (PMID 23617550, 2013). "And in vivo, strong secretion of IL-6, IL-8, and G-CSF or of IL-6, IL-8 and CCL-2, respectively, was observed following infection of cynomolgus macaques (Macaca fascicularis) with MPXV or CPXV, respectively." (PMID 23425254, 2013). "The results showed that greatest fold increases in mRNAs for CXCL10 and CCL2 were observed following infection of pigs." (PMID 24083897, 2013). "CCL2 is primarily produced by monocytes and macrophages and recruits monocytes to sites of active infection, exerting its effect through its receptor CCR2." (PMID 23265239, 2013). "To investigate differential inflammatory responses associated with Lmo-InlA-mur-lux and Lmo-EGD-lux infections, we measured serum levels of IFN-γ, IL-10, TNF-α, IL-6, CCL2, IL-5 and IL-1β at 3 and 5 days p.i. using Luminex bead arrays." (PMID 23617550, 2013). "CCL2 recruits monocytes, memory T cells and dendritic cells to the sites of tissue injury, infection, and inflammation." (PMID 23698783, 2013). "qPCR analysis indicated that the mRNA expression level of CCL2, one of the most potent chemoattractants of inflammatory Ly6Chi monocytes, was upregulated within hours after intrahepatic infection with E. histolytica." (PMID 23300453, 2013). "STAT5 induced expression of CSF2 results in increased production of monocytic chemoattractant protein 1 (CCL2) by monocytic cells, which functions in the recruitment of monocytic cells, including macrophages to the sites of injury or infection." (PMID 24339989, 2013). "In contrast, resistant C57BL/6J mice displayed low serum levels of IFN-γ, TNF-α, IL-6, and CCL2 at both timepoints of infection." (PMID 23617550, 2013). "Myd88/Trif-null mice exhibited a pattern of secretion of IFN-γ as well as IFN-γ induced chemokines mostly identical to C57BL/6 controls with a peak of CCL2 at day 4 of infection." (PMID 23762028, 2013). "Our results show that this process is facilitated by a known modulator of cellular infection and vascular permeability, bradykinin, and can be augmented by the chemokine CCL2." (PMID 24312535, 2013). "Using qPCR, we found a significant increase (P<0.04) in CCL2 mRNA expression levels in the livers of infected mice compared with control mice as early as 6 h and up to 24 h post-infection." (PMID 23300453, 2013). "Compared with medium control, mycobacterial infection of neutrophils and monocytes induced an ascendant CXCL8 and CCL2 secretion that peaked 3 h after infection." (PMID 22058091, 2012). "Ccl2 expression was downregulated by infection with both YopM-expressing and control Y. pestis strains (P < 0.05)." (PMID 23248776, 2012). "Accordingly, we included Tnfα, Ccl2, and Il6 among the genes evaluated with in-vitro infection models." (PMID 23248776, 2012). "Recruitment of inflammatory monocytes to the site of infection, that is driven by the chemokines MCP1 (CCL2) and MCP3 (CCL7), is an important mechanism supporting development of innate immunity against L. monocytogenes infection." (PMID 22629382, 2012). "Bone marrow mesenchymal stem and progenitor cells are the initial producers of CCL2 and inducers of monocyte emigration during infections." (PMID 22911155, 2012). "During infections with microbial pathogens, the initial CCL2 production is triggered in the BM, where it mediates inflammatory monocyte egression into the blood stream." (PMID 22911155, 2012).